DNAJB9 (DnaJ heat shock protein family (Hsp40) member B9)
Diseases named in the same sentence as DNAJB9 in open-access papers (continued):
Sharing a sentence is not in itself a finding about the gene and the disease.
tumor (14 papers, 2020 to 2025). "Recently, another study demonstrated that DNAJB9 blocked the tumor metastasis by enhancing Fbxo45-involved degradation of ZEB1 in TNBC cells." (PMID 35279684, 2022). "Furthermore, mRNA levels of Xbp1 and its known transcriptional target Dnajb9 were reduced in GA muscle of KPC tumor-bearing Xbp1mKO mice compared with GA muscle of KPC tumor-bearing Xbp1fl/fl mice." (PMID 40655023, 2025). "We utilized qRT-PCR to validate increased expression of various transcripts related to the IRE1α/XBP1 arm of the UPR, such as IRE1 (gene name: Ern1), Xbp1, Dnajb9, Edem1, and CHOP (gene name: Ddit3) in GA muscle of KPC tumor-bearing mice compared to control mice." (PMID 40655023, 2025). "DNAJB9 promoted FBXO45-induced degradation of ZEB1 and reduced the tumor metastasis in TNBC." (PMID 38773471, 2024). "Our analyses showed that the transcriptome associated with RASSF1, a tumor suppressor involved in cell cycle regulation and not previously linked to UPR, is highly correlated with the transcriptome of several UPR‐related genes, such as BiP/GRP78, DNAJB9, GRP94, ATF4, DNAJC3, and CHOP/DDIT3." (PMID 36723232, 2023).
cancer (11 papers, 2012 to 2025). A tumor composed of atypical neoplastic, often pleomorphic cells that invade other tissues. "Our study provides evidence for the feasibility of DNAJB9 as a potential therapeutic target for preventing cancer metastasis and a candidate metastasis inhibitor in other cancer types." (PMID 36499297, 2022). "Then we assessed the expression levels of DNAJB9 using the GENT database across diverse cancer and normal tissues." (PMID 33966034, 2021). "Because no drugs or chemicals enhance the activity of HSP protein for anti-cancer purposes, further study is needed to develop a therapeutic strategy for DNAJB9-dependent drugs against TNBC metastasis." (PMID 33966034, 2021). "For example, in HSP40 families, DNAJC9 positively correlated with cell proliferation across all cancer cell lines and 14 cancer lineages, while DNAJB9 negatively correlated with cell proliferation across all cancer cell lines, as well as 13 cancer lineages." (PMID 33225964, 2020). "In the DNAJB (HSP40) subfamily, DNAJB11 positively correlated with cell proliferation in 16 cancer types, while DNAJB9 negatively correlated with cell proliferation in 17 cancer types." (PMID 33225964, 2020). "Importantly, some DNAJB proteins, including DNAJB1/HDJ1, DNAJB4/HLJ1, DNAJB6/MRJ, DNAJB8, DNAJB9/MDG1/ERdj4, DNAJB11/ERdj3/HEDJ, and DNAJB12, are implicated in cancer progression." (PMID 34948322, 2021). "The alteration frequencies in cancer cell lines were as follows: CDKN1A (4%), DNAJB9 (6%), GABARAPL1 (5%), RAB1A (1.6%), and VAMP7 (0.6%), with amplification being the most common type of alteration." (PMID 41040512, 2025). "In the Cancer Cell Line Encyclopedia (CCLE) database, ATIC was found to be overexpressed, while CDKN1A, DNAJB9, EDEM1, and GABARAPL1 exhibited lower expression levels, aligning with the gene expression patterns observed in our model equations." (PMID 41040512, 2025). "Furthermore, we identified cancer-related genes aberrantly expressed in ccRCC (BRMS1L, CPEB3, DNAJB9, KIF3B, NFIB, PTPRJ, RBL2) and targeted by members of the miR-106b-25 cluster, suggesting that their dysregulation may be driven by these miRNAs." (PMID 40943553, 2025).
infection (10 papers, 2013 to 2024). The state of being infected such as from the introduction of a foreign agent such as serum, vaccine, antigenic substance or organism. "The significantly downregulated genes (NEAT1, TPM3, ZNHBA, CKLF, and OSBPL8) and the upregulated genes (ITMZC, IFNG, CD69, DNAJB9, and LYST) in NCAM1+FCGR3A+dNK cells after infection were also analyzed." (PMID 38730500, 2024). "Again, infection with MERS-CoV, but not SARS-CoV-2, significantly induced XBP1s and its downstream effector DNAJB9." (PMID 36125275, 2022). "This was consistent with significant upregulation of DNAJB9 and total XBP1 during infection with MERS-CoV but not SARS-CoV-2." (PMID 36125275, 2022).
kidney diseases (3 papers, 2015 to 2022). "None of the cases presented DNAJB9 expression, neither in the kidney diseases with structured glomerular deposits subgroup, nor in normal kidney tissue, or in other relevant diagnostic differential conditions." (PMID 36140202, 2022). "In our study, all these conditions, together with all the other kidney diseases and normal tissues included in our non-FGN control group, resulted negative to DNAJB9, further supporting its specificity in the FGN diagnostic workup." (PMID 36140202, 2022).
DNAJB9 also shares sentences with these, for which no sentence is quoted: glomerulopathy (3 papers); diabetes (2); Hyperglycemia (2); hyperlipidemia (2); malnutrition (2); melanoma (2); ZIKV infection (2); Abdominal obesity (1); Alzheimer disease (1); autoimmune disorders (1); colon cancer (1); degenerative joint diseases (1); Diabetic Nephropathy (1); diabetic retinopathy (1); Dyslipidaemia (1); dyslipidemia (1); endometrial cancer (1); epilepsy (1); focal and segmental glomerulosclerosis (1); hematological disorders (1); hepatocellular carcinoma (1); Hyperinsulinemia (1); Hypoglycemia (1); lipid metabolism disorder (1); malaria (1); membranous nephropathy (1); monoclonal gammopathy (1); nasopharyngeal carcinoma (1); neuroblastoma (1); Neurodevelopmental delay (1).
A further 8 diseases each share a sentence with DNAJB9 in 1 paper.